CD4 (CD4 molecule)
Diseases named in the same sentence as CD4 in open-access papers (continued):
Sharing a sentence is not in itself a finding about the gene and the disease.
malaria (continued). "Much research on the role of CD4+ T cells in malaria has focused on their abundant production of IFN-γ, and indeed, infected Ifng-/- mice have fewer splenic macrophages than wild-type mice during the acute phase of infection." (PMID 27923070, 2016). "In particular, patients with recurrent malaria presented significant reduction of CD4+, CD8+ T-cells and activated T-cells (CD69-expressing CD4+and CD8+ T-cells)." (PMID 27581163, 2016). "Flow cytometric analysis showed that the majority of PD1+CTLA4+CD4+ T cells in malaria patients were Foxp3- and CD25-, which indicates that they were not Foxp3+ natural Tregs (nTregs)." (PMID 27802341, 2016). "A depletion in the number of CD4+ T cells will therefore affect the cellular and humoral immune responses and consequently the immune responsiveness to malaria antigens." (PMID 27619013, 2016). "Proof-of-principle studies using this murine malaria parasite model showed that PyCMP is able to induce protective CD4+ T cells and high levels of functional antibodies." (PMID 27128437, 2016). "We next examined the ability of PD1+CTLA4+CD4+ T cells in malaria patients to produce cytokines in response to plasmodial antigens." (PMID 27802341, 2016). "Although IL-15 is known to induce production of IL-17 from CD4+ T cells, plasma IL-17 was suppressed in malaria monoinfected children and similar in the other groups." (PMID 27418744, 2016). "This study was aimed at determining the prevalence of malaria in PLWHIV in Yaounde, as wells as investigate the association between CD4+ T cell count and malaria." (PMID 27619013, 2016). "Surprisingly, despite the high expression of coinhibitory receptors, malaria-specific effector function was predominantly found in the PD1+CTLA4+CD4+ T cell population." (PMID 27802341, 2016). "In malaria patients, the percentage of Ki67+ cells among the CD4+ T cell population was 2–32%, compared to 0.1–4% in the healthy controls." (PMID 27802341, 2016). "While it is established that CD4+ T cells and parasite-specific antibodies are critical for protective immune responses to blood-stage malaria, the contribution of CD8+ T cells is less clear." (PMID 27930660, 2016). "CTLA4 and PD1 expression on CD4+ T cells were also compared between patients with an uncomplicated course of malaria (n = 13) and patients with severe cerebral malaria (n = 3)." (PMID 27802341, 2016). "In blood-stage malaria, IFN-γ has been implicated as the key cytokine driving effective immune responses, and circumstantial evidence associates CD4+ T cells producing IFN-γ with protection against P. falciparum blood-stage infection in humans." (PMID 27662621, 2016). "The prevalence of malaria parasitaemia was higher in participants with CD4+ T cell count below 200 cells/μl and lowest in participants with counts above 500cells/μl." (PMID 27619013, 2016). "Based on the more prominent role of CD4 T cells in adaptive immunity to S. Typhimurium in mouse models, we focused our attention on suppression of CD4 T cell memory during acute malaria." (PMID 26366739, 2015). "WHO also recommends CTX prophylaxis for anybody with a CD4 count <350 cells/μl, or clinical stage 3 and 4 disease and irrespective of CD4 count or clinical stage in areas of high malaria prevalence and/or severe bacterial infections." (PMID 25600931, 2015). "Participants with malaria had CD4 cell count ranged 3 and 512 Cells/μl with the mean being 186.33 (±133.49) Cells/μl." (PMID 25857950, 2015). "The other four had known HIV [with an average CD4 count at the time of the malaria diagnosis of 394/mm3 (IQR: 239–405)]." (PMID 26383771, 2015). "With increased surface expression of PD1 on memory CD4 T cells, the phenotypic traits of Salmonella vaccine-induced memory T cells during malaria share characteristics of exhausted CD4 T cells identified during chronic viral infection." (PMID 26366739, 2015).
malaria (continued). "Studies in mice and human have indicated that both the helper and effector functions of CD4 T cells contribute to immunity against malaria." (PMID 26505634, 2015). "Clinicians most often doubted the quality of haematology (67%), followed by malaria (53%) and CD4 (22%) test results." (PMID 27213139, 2015). "The high plasma level of IL-10 in eBL, and the high frequency of CD4+CD25hi+ Treg cells in malaria and eBL, give credence to the parallel between dysregulation of the immune system in the two diseases." (PMID 28536409, 2015). "Malaria has been implicated in the increase of HIV-1 viral load and, as a result, a decrease in CD4+ T cells, high rates of HIV-1 transmission and rapid disease progression to AIDS." (PMID 26173396, 2015). "In cases of imported malaria, it has been observed that there is a higher risk of severe malaria almost exclusively in patients with HIV infection and CD4 counts under 350/mm3." (PMID 26383771, 2015). "The models examined the probability of being protected against malaria by either CS antibodies alone (model 1) or the combination of CS antibodies, CD4 T-cells expressing ≥ 2 cytokine/activation markers, and IFN-γ ELISpot (model 2)." (PMID 26148007, 2015). "CD4+ T cells contribute to protection against blood-stage malaria though induction of antibody production and macrophage activation." (PMID 25760084, 2015). "CD4+ T cells are known to be important in the protective immune response to blood-stage malaria, and we confirmed that CD4+-T-cell-depleted mice displayed greater parasitemia and a higher mortality rate." (PMID 25760084, 2015). "Addition of 3 well-defined malaria-specific human T cell domains to the hybrid VLPs enhanced protective efficacy in the liver as well as primed malaria-specific CD4+ T cell cytokine production." (PMID 25933001, 2015). "The prevalence of IFN-γ-producing CD4+ and CD8+ T cells has been associated with a greater likelihood of uncomplicated malaria, as well as reduced severe malarial anemia in humans." (PMID 26426121, 2015). "The median frequency of CD4+CD25hi+ Treg cells were higher in both malaria and eBL patients compared to healthy controls (p = 0.000 and p = 0.027, respectively)." (PMID 28536409, 2015). "The presence of parasite-specific CD4+ T cells correlates with reduced parasite burdens and disease severity in malaria, but the effect of parasites on Treg cell induction is the opposite." (PMID 26438270, 2015). "Our data uncover a mechanism by which CD4+ T cells and B cells control parasitemia during chronic erythrocytic-stage malaria through a single gene, Il21, and demonstrate the importance of this cytokine in the control of pathogens by humoral immune responses." (PMID 25763578, 2015). "A questionnaire was administered and 2 ml of venous blood samples were drawn for malaria parasites detection, CD4 count and haemoglobin level estimations." (PMID 25857950, 2015). "During acute malaria, it is likely that a defect in memory CD4 T cell effector function acts together with other malaria-induced defects in innate immunity to compromise established adaptive immunity acquired either by vaccination or from previous infections." (PMID 26366739, 2015). "The study also showed malaria causes increased HIV viral load in blood and breast milk and reduced CD4 cell count." (PMID 26671012, 2015). "The most common tests were: malaria parasites; fullblood count; blood grouping and cross matches; and CD4 count." (PMID 38440308, 2015). "Other reasons reported included: doubting laboratory expertise, especially for CD4 count results (n = 9; 22%) and malaria results (n = 20; 18%)." (PMID 27213139, 2015). "Accordingly, ablation of PD-1 pathway contributes to IFN-γ production and functional restoration of CD4 T cells, correlated with clearance of blood stage malaria in mice." (PMID 25803808, 2015).
malaria (continued). "Helper T-cells, CD4+ regulates the immune response against malaria by proliferation and production of cytokines, and activation of B cells to produce parasite specific antibodies." (PMID 26173100, 2015). "Perturbations of T cell subsets in severe malarial anemia and uncomplicated malaria resulted in increased proportions of children with reversed CD4/CD8 ratios (ratio of <1.0)." (PMID 26581890, 2015). "Median ratios of memory to naive CD4+ lymphocytes were higher in cerebral malaria than in uncomplicated malaria and low in severe malarial anemia." (PMID 26581890, 2015). "Approximately half requested repeat malaria testing (n = 110; 53%), whilst the CD4 count test had the least frequency (n = 41; 22%) of repeat requests." (PMID 27213139, 2015). "Four were diagnosed with HIV at the time malaria was diagnosed, with an average CD4 of 221/mm3 (IQR: 51–325)." (PMID 26383771, 2015). "While there is a predominantly Th1 cytokine profile in CD4 T cells in healthy rural African individuals who are exposed frequently to malaria, these T cells also express high levels of IL-10 and IL-21." (PMID 26646149, 2015). "The results showed an increase in the percentage of CD4+ T cells in early apoptosis (Annexin V+) in P. vivax-infected donors (3.11%) compared to malaria-naive donors (0.34%) (p < 0.0001)." (PMID 25559491, 2015). "IL-21-producing CD4+ T cells are present in peripheral blood mononuclear cells from malaria-exposed immune adults and correlate with P. falciparum-specific IgG antibodies in children with acute falciparum malaria." (PMID 25763578, 2015). "If the immunopathology of cerebral malaria results from priming of T lymphocytes by previous exposure to malaria, activation would be anticipated most in the adaptive CD4+ and CD8+ lymphocyte populations." (PMID 26581890, 2015). "In the context of murine malaria models, CD4 T cells were shown to be an important cellular source of immunomodulatory IL-10." (PMID 24787713, 2014). "Together these data suggest that recency of malaria infection, rather than the total number of past episodes, exerts a dominant influence on the functional phenotype of malaria-specific CD4+ T cells." (PMID 24415936, 2014). "One of the first studies to examine PD-1 expression during malaria used a mouse model to show PD-1 expression on IL-7Rlo-expressing CD4+ and CD8+ T cells." (PMID 24904561, 2014). "Malaria infected red blood cells (iRBCs) induced CD4+CD25hiFOXP3+ Tregs in vitro in healthy human volunteers." (PMID 25309517, 2014). "A prospective study found significant increases in mean CD4 counts (297 to 447/μL) and decreases in the proportion of patients with a CD4 T-cell count less than 200/μL (28.7% to 13.2%) after successful malaria treatment in HIV-infected individuals." (PMID 24729787, 2014). "The CD4+ T cell activation level during the malaria phase was also negatively correlated with the iDNA levels in PBMCs (P = 0.005, r = −0.458)." (PMID 25487036, 2014). "We show in this article that children who induced DBLα-tag specific IL-4+CD4+ T cell responses had a delayed time to subsequent malaria episodes over the next year." (PMID 24453249, 2014). "During malaria, CD4+ T cell subsets have multiple roles in protection, pathogenesis and also escape from immune responses." (PMID 24904561, 2014). "The mechanisms of direct versus cross-presentation, CD4+ T cell priming and the delivery of help via licensed APCs or otherwise collectively define the problem with respect to liver-stage malaria vaccine strategies." (PMID 25426113, 2014). "As expected, malaria activated the CD4+ T cells, decreased the integrated virus DNA (iDNA) load in peripheral blood mononuclear cells (PBMCs) and reduced the replication-competent virus pool in resting CD4+ T cells." (PMID 25487036, 2014). "The highest prevalence of malaria parasitaemia (31.5%) was observed among the group that had the highest CD4+ T-cell count and the difference was statistically significant." (PMID 24729787, 2014).
malaria (continued). "In a different rodent model of erythrocytic-stage malaria, P. yoelii 17X(NL), although activation of T-bet was detected on CD4+ T-cells early in infection, the infection can still be controlled in T-bet-deficient mice." (PMID 25628621, 2014). "We have highlighted the apoptosis of memory CD4+ T cells during Pc infection, which is a potential outcome of the activation of these cells induced by malaria." (PMID 25487036, 2014). "Next, we analyzed the intracellular expression of Foxp3 during the first infection to detect natural Tregs, defined as CD4+CD25highFoxp3+ cells and reported to regulate the immune response in malaria." (PMID 24465641, 2014). "Contrary to our observation, many studies have reported that malaria coinfection with HIV decreases CD4+ T cells counts." (PMID 24729787, 2014). "Of particular note is that even though PD-1 KO mice had more functional CD4+ T cells than WT mice and similar titers of parasite-specific antibodies, they still developed chronic malaria if CD8+ T cells were depleted." (PMID 24904561, 2014). "Herein, we discuss activation of different CD4+ T-cell subsets during malaria, their role in the control of the infection and the interplay between different subsets, with a particular emphasis on the concept of CD4+ T-cell plasticity." (PMID 25628621, 2014). "We confirmed that cys2 DBLα-tags induced CD4+ T cells that predominantly secrete IL-10 during the acute malaria episode." (PMID 24453249, 2014). "P. falciparum-inducible IFN-γ- and TNF-producing CD4+ T cells also increased after the resolution of malaria compared to baseline, and like IL-10, reverted to homeostasis after the dry season." (PMID 24743880, 2014). "Similar to IL-10 producing CD4+ T cells, plasma IL-10 strongly correlated with recent malaria (Spearman's Rho = 0.30, P = 0.009)." (PMID 24415936, 2014). "The pattern of cytokine production by malaria-specific CD4+ T cells was noted to differ markedly based on children's prior incidence of malaria." (PMID 24415936, 2014). "We assessed proliferation of malaria-specific CD4+ T cells by measuring CFSE dilution following stimulation with schizont extract (PfSE) in a subset of children (n = 42)." (PMID 24415936, 2014). "IL-10, important to counterbalance inflammation and associated with protection from inflammatory-mediated severe malaria in both humans and experimental models, was originally considered be produced by CD4+ Th2 cells during infection." (PMID 25628621, 2014). "Immunity to blood stage malaria parasites is thus primarily conferred by humoral immune responses in which the participation of IL-4 producing CD4 Th2 cells and B cells are of major importance." (PMID 24465641, 2014). "Our results suggest that the functional phenotype of the malaria-specific T cell response was heavily influenced by prior malaria exposure intensity, with CD4+ T cells co-producing IFNγ and IL10 dominating this response among highly exposed children." (PMID 24415936, 2014). "The median frequency of malaria-specific CD4+ T cell responses producing any of these cytokines, alone or in combination, was 0.20% (IQR 0.12%–0.35%)." (PMID 24415936, 2014). "An earlier study in Uganda had already shown that ART associated to daily cotrimoxazole was protective against malaria-related fever, compared to daily cotrimoxazole alone, in a population of HIV-infected adults and adjusted for the CD4 cell count." (PMID 24996807, 2014). "We also analyzed the relationship of prior malaria incidence with the “composition” of the malaria-specific response (i.e. the proportion of each cytokine combination amongst the total malaria-specific CD4+ T cell population), and found similar results." (PMID 24415936, 2014). "We also observed that the number of iDNA copies in PBMCs during the malaria phase was negatively correlated with the apoptosis levels of CD4+ TCM cells in the two groups (P = 0.025, r = −0.372)." (PMID 25487036, 2014).
malaria (continued). "Some studies suggest an association between cell-mediated immune responses (specifically CD4 T cell responses) and protection against clinical malaria in children, albeit of lesser importance than antibody responses." (PMID 25506706, 2014). "CD4+ T cell IFNγ/IL-10 responses to the polyclonal mitogen PMA/Io have previously been shown to correlate with relative protection against severe malaria." (PMID 24415936, 2014). "Almost all children induced DBLα-tag specific CD4+ T cells secreting any of the cytokines measured during the acute malaria episode and 62% maintained effector cells for over 6 mo suggesting that effector memory T cells had been induced." (PMID 24453249, 2014). "The frequencies and numbers of CD4+ CD25high cells were early increased in mice with fatal malaria, while in healthy mice numbers remained at levels of 1.90±0.10×105 cells/ml in blood that accounted for a 1.21±0.07% of total WBCs." (PMID 24465641, 2014). "The potential role that malaria-specific IFNγ/IL-10 co-producing CD4+ T cell cells play in mediating or inhibiting protective immunity in humans has not thus far been investigated." (PMID 24415936, 2014). "In the multivariate analysis of factors associated with confirmed and suspected malaria-related fever episodes, ART initiated before inclusion appeared to be a protective factor, even after adjusting for baseline CD4 count." (PMID 24996807, 2014). "CD4+ T cells have been demonstrated to be the major source of both interferon-γ (IFN-γ) and tumor necrosis factor alpha (TNF-α) during experimental malaria in mice which are implicated in both protection and pathology of this disease." (PMID 24904561, 2014). "The sources of immunomodulatory IL-10 in the P. yoelii and P. chabaudi malaria models are populations of CD4 T cells." (PMID 24787713, 2014). "We therefore analyzed CD4+ T cell responses to homologous DBLα-tags in a cohort of children under active surveillance for acute malaria episodes." (PMID 24453249, 2014). "On the other hand, the proportion of febrile episodes referred as confirmed or suspected malaria-related fever was higher in women with a CD4 cell count <350/mm3 (31%) than in women with a CD4 cell count ≥350/mm3 (14%, p = 0.03)." (PMID 24996807, 2014). "The clinical course of the P. knowlesi malaria case described here was uncomplicated despite marked immunosuppression of the patient (115 CD4 positive cells/μl)." (PMID 23941258, 2013). "This will impact a cross section of other sample types (chemistry, hematology, CD4, sputum, and malaria smears) with similar transportation challenges." (PMID 24236026, 2013). "Women with low levels of CD4+ T cells (< 350 cells/μl) however, have a reduced ability to mount protective immune responses to either malaria or other infections." (PMID 24007344, 2013). "The induction of CD4+CD25+Foxp3+ regulatory T cells (Tregs) by malaria parasites has been described and is related to the ability of parasites to escape from both protective and harmful host immunity, especially concerning splenic T cells response." (PMID 23646169, 2013). "It was also observed a positive relation between ANXA1 expression and the number of previous episodes of malaria in CD4+ T cells." (PMID 24359168, 2013). "The aim of this study was to investigate the annexin-A1 expression in CD4+, CD8+ T cells, regulatory T cells (Treg) and cytokine IL-10 quantification in plasma from patients with malaria caused by P. vivax." (PMID 24359168, 2013). "Considering the importance of activated macrophages and IFN-γ for the control of blood stage malaria, the in vivo effects of hemin on mouse macrophages and CD4 T cells were investigated." (PMID 23358441, 2013). "With regard to malaria, the topical administration of imiquimod with the PfCS peptide elicited strong parasite-specific antibody production, CD4+ T cell responses, and protection in a rodent challenge model." (PMID 23710439, 2013).